POU5F1 (POU class 5 homeobox 1)
Diseases named in the same sentence as POU5F1 in open-access papers (continued):
Sharing a sentence is not in itself a finding about the gene and the disease.
tumor (continued). "Suggesting that POU5F1 may be a new tumor biological and prognostic marker and can be used as a potential therapeutic target." (PMID 38062041, 2023). "Some results have shown that POU5F1 can enhance tumor drug resistance." (PMID 38062041, 2023). "Moreover, POU5F1 was observed to enhance the proliferation, migration, and invasion of GC cells in vitro, as well as promote subcutaneous tumor growth and lung metastasis of GC cells in vivo." (PMID 38062041, 2023). "Through the HPA database, we found that three genes, namely ABCC9, AHNAK, and DIP2C, had low expression in patients with tumours, and eight other genes—PLOD1, SLC3A2, RUNX2, RAD9A, CHMP4C, DARS2, CLIC3, and POU5F1—were highly expressed in patients with tumours." (PMID 36685927, 2022). "Besides, the pooled estimates of clinicopathological parameters suggested that POU5F1 played pivotal roles in tumorigenesis, tumor growth, invasion, metastasis, and therapy resistance in multiple cancers." (PMID 32978904, 2020). "POU5F1 may influence the progression of LIHC by regulating the tumor immune microenvironment and participating in cell proliferation‐related pathways." (PMID 32978904, 2020). "Moreover, METTL3 or IGF2BP2 expression positively correlated with the SOX2 downstream genes CCND1, MYC, and POU5F1 in our independent cohort of paired CRC tumor and adjacent normal tissues from SYSUCC." (PMID 31230592, 2019). "ITE significantly reduced the POU5F1 mRNA levels in tumours, the tumour volumes as well as the tumour weights, and there was a positive correlation between the POU5F1 mRNA level/tumour volume and the POU5F1 mRNA level/tumour weight when all the mouse samples were analysed together." (PMID 26059097, 2015). "Additionally, POU5F1 promotes tumor proliferation, migration, invasion, and tumorigenicity." (PMID 40927570, 2025). "The expression of POU5F1, a key regulator of stem cell pluripotency, substantially increased, while the expression of CBX7, a gene that encodes a Polycomb protein which globally regulates cellular lifespan and is a tumor suppressor in both mice and humans, decreased towards ESC/iPSCs." (PMID 35587924, 2022). "Our study found that there was a prominent decrease in B cells naive and an increase in B cells memory in the high POU5F1 group of LIHC tumor tissues, hinting that the elevated POU5F1 might promote the transformation of B cells naive into B cells memory in LIHC." (PMID 32978904, 2020). "POU class 5 homebox 1 (POU5F1) expression is associated with tumorigenesis (RefSeq: 5460), and C-X-C motif chemokine ligand 12 (CXCL12) encodes a protein that functions in many diverse cellular functions including tumor growth and metastasis (RefSeq: NG_016861.2)." (PMID 32649728, 2020). "In addition, POU5F1 (HR = 1.64, p = .038) was identified as an independent risk factor for OS of LIHC through multivariate analysis, as were tumor stage (HR =1.51, p < .001), tumor invasion depth (HR = 1.51, p < .001), and distant metastasis (HR = 3.73, p = .026)." (PMID 32978904, 2020). "While three genes (AHNAK, ABCC9, and DIP2C) were highly expressed in normal tissues, eight genes (CHMP4C, CLIC3, DARS2, PLOD1, POU5F1, RAD9A, RUNX2, SLC3A2) were highly expressed in tumour tissues." (PMID 36685927, 2022). "Through the HPA database, we found that three genes (ABCC9, AHNAK, and DIP2C) had low expression in patients with tumours, whereas eight genes (PLOD1, SLC3A2, RUNX2, RAD9A, CHMP4C, DARS2, CLIC3, and POU5F1) were highly expressed." (PMID 36685927, 2022).
tumor (continued). "We identified upregulated POU5F1 as an independent prognostic factor for poor prognosis of LIHC through Cox regression, along with tumor stage, invasion depth, and distant metastasis." (PMID 32978904, 2020). "Taking advantage of the distinct origin of tumor (human) and stromal (murine) cells in our xenografts, we approached the evaluation of stemness genes NANOG, POU5F1 (OCT4), PROM1 (CD133) and SOX2, from the tumor origin." (PMID 32230715, 2020). "Recently, scientists have investigated several key factors for stemness and spheroid formation, including POU5F1 (Oct4), KLF4, SOX2 and Nanog, the activation of which induces several canonical pathways involved in tumor relapse after treatment." (PMID 32188842, 2020). "Expressed as a pluripotency gene in TGCTs, like other genes as POU5F1 and NANOG, it takes part in regulating gametogenesis, differentiation, sexual determination and in tumor pluripotency." (PMID 29416701, 2018). "Remarkably, Oct3/4 (POU5F1), which was recently described as a new BTIC marker, is also expressed in our tumor model." (PMID 28249000, 2017). "The immunostaining of tumor spheroids confirms the findings at the tissue level, with a strong expression of POU5F1/OCT4, particularly in FTC spheroids." (PMID 28039458, 2017). "We confirmed higher expression of pluripotency transcription factors (NANOG, POU5F1, SOX2) and CD133 in cells forming tumor spheres." (PMID 27934912, 2016). "GCSs-enriched spheres expressed higher levels of pluripotency markers: NANOG, POU5F1, SOX2 and CD133 as compared to the adherent tumor cells." (PMID 27934912, 2016). "In conclusion, our study demonstrates that POU5F1 and MMP-2 contribute to tumor invasion and migration phenotype of LACSLCs, and aberrantly high expression of POU5F1 can enhance MMP-2 expression by directly targeting the promoter of MMP-2." (PMID 24386189, 2013). "After stimulation with various concentrations of BCE (62.5, 125, 250, 500 or 1,000 μg/ml) for 24 and 72 h, tumor cells were analyzed by qRT-PCR or western blot analyses for the expression of the stem cell genes NANOG, POU5F1 and SOX2, respectively." (PMID 23969837, 2013). "OCT4, a transcript of POU5F1, plays a role in maintaining stem cell pluripotency, self-renewal and chromatin structure in stem cells, and promotes tumor growth in a dose-dependent manner." (PMID 19857256, 2009). "The tumor with an EWSR1::POU5F1 fusion (case 7) contained nested clear to eosinophilic tumor cells with EMA and S100 expression but was negative for other myoepithelial markers." (PMID 39636306, 2025). "However, the expression of CD133/PROM1, OCT4/POU5F1, KLF4, and MYC occurred more frequently compared to EPCAM-negative tumor spots." (PMID 39456890, 2024). "Although we used data from the TCGA and despite our efforts, we were not able to confirm in the TCGA dataset our findings of reduced POU5F1 gene expression in tumor samples compared with non-tumor controls at a statistically significant level." (PMID 37409260, 2023). "The TCGA results indicate a non-significant trend of the increase of the POU5F1 expression from normal tissue to primary tumor and to metastases." (PMID 37409260, 2023). "Notably, IL20RB overexpression upregulated the mRNA levels of several tumor stemness markers, including NANOG, SOX2 and POU5F1, while IL20RB knockdown downregulated their mRNA levels." (PMID 38098005, 2023). "In a syngeneic murine tumor model, mice bearing MBT-2 tumors treated with an oncolytic adenovirus, Ad5WS4 (E1B-55 kD-deleted adenovirus driven by the POU5F1 promoter), significantly suppressed tumor growth and prolonged survival as compared to the control group." (PMID 37627900, 2023). "Eight genes (SLC3A2, DARS2, DIP2C, PLOD1, RUNX2, ABCC9, AHNAK, and CLIC3) may be involved in the malignant transformation of tumours, and three genes (CHMP4C, POU5F1, and RAD9A) may have a protective effect in patients with tumours." (PMID 36685927, 2022).
tumor (continued). "The BCPRS-related genes (YY1, POU5F1, NKX2-3, NR2F1, HEY1, and IFNA13) showed high heterogeneity in different cells; thus, the genes can independently predict cellular composition to reflect the microenvironment of tumor tissues." (PMID 34457116, 2021). "Furthermore, when endogenous ELK-1 was silenced in the primary tumor culture of patient 624 (middle level of ELK-1 expression), CD133, NANOG, SOX2, and POU5F1 levels were all downregulated as compared to scramble RNA control." (PMID 33672811, 2021). "For the castration-induced regression nadir group (i.e., those with the weakest or most unsuccessful castration-induced tumor regression), GSE1, CYP3A5, CTNNB1, CYP3A4, POU5F1, ABCB1, alkaline phosphatase liver/bone/kidney isozyme (ALPL), PROM1/CD133, ABCG2, and SOX2 were concomitantly upregulated." (PMID 34439112, 2021). "For in vivo experiments, a xenograft model where OSCC cells stably expressing ADAR1 were implanted was used to investigate the effect of ADAR1 on tumor growth and progression, and the expression of ADAR1, PCNA, SOX2 and POU5F1 was further detected by immunohistochemistry." (PMID 31315644, 2019). "SP cells exhibited greater tumor-initiating ability and higher expression levels of iPS cell-related genes (SOX2, POU5F1 and NANOG), indicating that SP cells derived from LHK2, SW480 and MCF7 cells are enriched with CSCs/CICs and are a reasonable source for further research." (PMID 24244262, 2013). "Additionally, POU5F1, LGR5 and CCND1 were analysed, and tumour samples of patients with TRG2 or TRG3 (each n = 22) were studied." (PMID 22970250, 2012). "Further analysis of the primary tumor by RT-PCR revealed the expression of the pluripotency markers POU5F1, NANOG and SOX2 in CD44+ but not CD44− subpopulations." (PMID 21124918, 2010). "In situ sequencing also confirmed a consistent pattern: in EpCAMhigh tumor cell-dominated spots, compared to EpCAM-negative cell-dominated spots, there was a more frequent expression of the CD133/PROM1 gene along with the transcription factor genes OCT4/POU5F1, KLF4, and MYC." (PMID 39456890, 2024). "The tumor-restricted TcGT most frequently detected in our cohort initiated within a primate-specific LTR66 endogenous retroviral promoter on chromosome 8q24, spliced into several other TE inserts (AluSx1, LTR33, L2b, and MLT1F1) and ended in POU5F1B, a paralog of the POU5F1/OCT4 pluripotency gene." (PMID 35987910, 2022). "Moreover, recent studies revealed that POU5F1 expression was significantly elevated in tumor tissues compared to non-cancerous tissues." (PMID 36251702, 2022). "Although genetic changes may affect the level of mRNA expression, the findings of this study showed no significant variation in tumor copy number and nucleotide mutations of the six IMAAG genes (HEY1, IFNA13, NKX2-3, NR2F1, POU5F1, and YY1)." (PMID 34457116, 2021). "Notably, we identified new downstream target genes in 925 upregulated genes, including ZEB1, POU5F1, and MED1, which could be important factors in tumor metastasis and the maintenance of CSCs." (PMID 30674889, 2019). "Moreover, immunohistochemical examination revealed that POU5F1/Oct-4 expression was significantly elevated in tumor tissues compared to adjacent non-cancerous tissues." (PMID 26931354, 2016). "Oct4 (Oct3/4 or POU5F1), an embryonic stem cell factor and member of the POU family of transcription factors, has been extensively studied in solid tumours including those of the lung, brain, and breast where it has closely been related to tumour progression, self-renewal and drug resistance." (PMID 26260289, 2015). "In addition it could be demonstrated that inhibition of proliferation is associated with downregulation of the known stem cell factors NANOG, POU5F1 and SOX2 in tumor cells." (PMID 23969837, 2013). "Indeed, the Pou5f1 gene is specifically expressed in embryonic stem cells and in tumor cells, but not in cells of differentiated tissues." (PMID 21464922, 2011).
tumor (continued). "Therefore, our analysis did not identify some tumour markers such as POU5F1, FLJ10884 and AK3, because they already were upregulated in the CIS cells." (PMID 15856041, 2005). "Thus, high expression of POU5F1, ALDH1, and SOX2 in enzalutamide-resistant cells and samples from androgen deprivation therapy-treated patients may signify a stem-cell-like state, granting tumor cells significant lineage plasticity and enabling them to evade immune and targeted therapies." (PMID 40821114, 2025). "In contrast to the POU5F1, the correlations between the AHR mRNA level and the tumour volume/tumour weight were not significant in the vehicle group but remarkably increased in the ITE group." (PMID 26059097, 2015). "Heatmap analysis of gene expression in adherent cells and stem‐like tumor spheres revealed a negative correlation between YY2 and stem‐related factors, including CD44, SOX9, SALL2, KLF15, OCT4 (also known as POU class 5 homeobox 1 or POU5F1), MYC, ASCL1, and POU3F2." (PMID 37300334, 2023).
infection (60 papers, 2009 to 2025). The state of being infected such as from the introduction of a foreign agent such as serum, vaccine, antigenic substance or organism. "As expected, infection with Pou5f1-mCherry vector induced both Pou5f1 and Ascl1 expression in Notch1/2-deficient Müller glia." (PMID 40388211, 2025). "Unlike in control (GlastCreER;Rosa26LSL-Sun1-GFP) retinas, Pou5f1-expressing, Rbpj-deficient Müller glia showed no EdU incorporation at either 1, 2, or 5 weeks following infection." (PMID 40388211, 2025). "Infection of human iPS cells with lentivirus expressing Cas9-sgRNA followed by puromycin selection for guide expression did not alter expression of key transcriptional markers of pluripotency, POU5F1, Nanog or Sox2 or iPS cell proliferation rate relative to uninfected cells." (PMID 34230586, 2021). "In order to determine whether the ability of RA and cDDP to down-regulate the expression of NANOG and POU5F1 is essential to their ability to acutely induce resistance to cDDP, NT2-D1 cells were molecularly engineered to constitutively express NANOG by infection with a retroviral expression vector." (PMID 24475288, 2014). "Our results showed that the infection did not change the mRNA expression of SOX2, NANOG, and POU5F1, but increased the mRNA expression of TLR4 and the cell surface expression." (PMID 40573358, 2025).
adenocarcinoma (20 papers, 2010 to 2025). A common cancer characterized by the presence of malignant glandular cells. "Liu et al100 demonstrated that during the transition from adenocarcinoma to undifferentiated small-cell carcinoma, POU5F1, lin-28 homolog A (LIN28A), SOX2, and NANOG are sequentially activated, driving the transformation of differentiated adenocarcinoma to undifferentiated small-cell carcinoma." (PMID 40821114, 2025). "Patients with adenocarcinoma mainly contributed to the alteration of plasma anti‐POU5F1 IgG levels." (PMID 32392378, 2020). "In contrast, adenocarcinoma LuCaP lines are generally negative for scTF except POU5F1, and are B2Mhi." (PMID 34911496, 2021). "Expression heterogeneity was also found among LuCaP adenocarcinoma lines regarding the scTF genes – many with POU5F1, a few with LIN28A, none with SOX2 and NANOG." (PMID 31146720, 2019).
POU5F1 also shares sentences with these, for which no sentence is quoted: non-small cell lung carcinoma (33 papers); breast tumors (24); esophageal squamous cell carcinoma (24); oral squamous cell carcinoma (24); endometrial cancer (18); teratocarcinoma (18); endometriosis (17); esophageal cancer (14); brain tumors (12); ovarian tumors (11); rectal cancer (11); renal carcinoma (10); metastatic tumors (8); nasopharyngeal carcinoma (8); astrocytomas (7); bladder tumors (7); Hyperglycemia (6); ovarian endometriosis (6); viral infection (6); breast invasive carcinoma (5); cholangiocarcinoma (5); chronic myeloid leukemia (5); Infertility (5); Obesity (5); triple-negative breast carcinoma (5); yolk sac tumor (5); adenomyosis (4); Azoospermia (4); bladder transitional cell carcinoma (4); colon adenocarcinoma (4).
A further 266 diseases each share a sentence with POU5F1 in 4 papers or fewer.